MYADM-AS2 (MYADM antisense RNA 2)
Synonyms: VEAL2
Gene: Long non-coding RNA gene on chromosome 19 (53,869,654 to 53,876,435, reverse strand). Ensembl gene ENSG00000232220.
Diseases named in the same sentence as MYADM-AS2 in open-access papers:
MYADM-AS2 is named in the same sentence as 7 diseases in open-access papers, as found by Europe PMC text mining. Sharing a sentence is not in itself a finding about the gene and the disease.
MYADM-AS2 shares sentences with these, for which no sentence is quoted: diabetes (1 paper); diabetic retinopathy (1); endothelial dysfunction (1); hemorrhage (1); Hyperglycemia (1); tumor (1); type 2 diabetes mellitus (1).